COL4A2 (collagen type IV alpha 2 chain)
Diseases named in the same sentence as COL4A2 in open-access papers (continued):
Sharing a sentence is not in itself a finding about the gene and the disease.
Pulmonary hemorrhage (1 paper, 2025). Pulmonary hemorrhage is a bleeding within the lungs. "The COL4A2 gene mutation affects vascular endothelium integrity, causing pulmonary hemorrhage." (PMID 40598578, 2025). "Although this mutation and pulmonary hemorrhage have not been previously reported, the COL4A2 gene has been associated with vascular events, such as cerebral hemorrhage." (PMID 40598578, 2025). "Two novel and two pathogenic mutations in COL3A1 gene associated with vEDS, COL1A1, COL1A2, TNXB gene mutations of non-vascular types underlying EDS and COL4A2 gene associated with collagen synthesis were found in patients presenting with pulmonary hemorrhage." (PMID 40598578, 2025).
Skeletal myopathy (1 paper, 2018). "Importantly, postnatal treatment with 4PBA also reduced ICH and skeletal myopathy severities in Col4a1 mutant mice, which has significant clinical implications for patients with COL4A1 and COL4A2 mutations." (PMID 29895609, 2018).
thyroid cancer (1 paper, 2024). "This study was to preliminarily investigate the effects of the COL4A2 gene on the regulation of thyroid cancer (THCA) cell proliferation and the associated pathways." (PMID 39220121, 2024). "Next, on the basis of our raw letter analysis, we investigated the role of the AKT pathway in COL4A2-related thyroid cancer development." (PMID 39220121, 2024). "Our findings also suggested that COL4A2 inhibitors may be used to develop new therapies for thyroid cancer." (PMID 39220121, 2024).
type 2 diabetes (1 paper, 2021). "Four core genes (COL4A2, ACACB, GLUL, and CD36) were found to be highly expressed in subcutaneous adipose tissue of obese patients accompanying type 2 diabetes." (PMID 34085602, 2021).
unstable angina (1 paper, 2022). "The aim of this study was to evaluate the association between the PECAM1 (rs1867624), COL4A2 (rs4773144), PHACTR1 (rs9349379) and LMOD1 (rs2820315) gene polymorphisms and the risk of unstable angina." (PMID 35054067, 2022).
Uterine leiomyoma (1 paper, 2013). The presence of a leiomyoma of the uterus. "In the present study, the gene expressions of COL4A1, COL4A2 and COL6A3 were found to be increased in uterine leiomyomas." (PMID 23818951, 2013).
tumor (62 papers, 2005 to 2026). "The COL4A2 gene is implicated in angiogenesis and tumour growth suppression and previous work has reported specific changes in its genomic sequence that cause familial and sporadic small vessel disease." (PMID 36757925, 2023). "The search for the upregulated genes in three types of CSCs revealed Actn3, Ccnd2, Col4a1, and Col4a2, which have been linked to tumor aggressiveness, poor prognosis, cancer cell proliferation, and cell migration." (PMID 35063003, 2022). "The COL4A1 and COL4A2 had the most significant association with tumor grade (AUC = 0.822 and 0.820 in G2 vs G3 and G4; AUC = 0.863 and 0.834 in G3 vs G4), followed by COL4A3 and COL4A4 (AUC = 0.539 and 0.585 in G2 vs G3 and G4; AUC = 0.677 and 0.753 in G3 vs G4)." (PMID 40351420, 2025). "Protein–protein interaction analysis suggested that IGFBP4 is associated with IGF1, IGF2, and extracellular matrix associated proteins such as COL4A2, which was a significant factor affecting tumor metastasis and implying that IGFBP4 affects cell invasion through the IGF signaling pathway." (PMID 37349627, 2024). "Therefore, the increased vessel formation in tumors may be associated with the upregulation of COL4A1 and COL4A2 expression, and the aggressiveness of the tumor may result in the downregulation of COL4A3 and COL4A4 expression and minor Col IV degradation to promote invasion of tumors." (PMID 40351420, 2025). "EC5 displayed high expression levels of genes related to ECM remodeling (COL4A1,COL4A2,HSPG2,MMP2,SPARC),which have been previously implicated in tumor angiogenesis." (PMID 41394809, 2025). "The results demonstrated that COL4A1 and COL4A2 exhibited higher expression levels in tumor samples compared to normal tissues." (PMID 38907304, 2024). "Immunohistochemistry (IHC) revealed that the expression of COL4A2 in tumor tissue was significantly greater than normal, and COL4A2 was divided into high and low-expression." (PMID 39220121, 2024). "Subsequently, we performed a protein blot analysis to evaluate the differences in COL4A2 expression between THCA tumor tissues and paired adjacent normal tissues and found that COL4A2 expression was greater in both THCA tumor tissues." (PMID 39220121, 2024). "To validate the mRNA expression pattern, we compared the protein expression levels of COL4A1 and COL4A2 between tumor cells and normal cells." (PMID 38907304, 2024). "Upregulation of COL4A2 gene expression in 2 THCA cell lines promoted tumor cell growth and activity." (PMID 39220121, 2024). "Subsequently, after determining the expression of COL4A2 in tumor tissues and paracancerous tissues in the GSE5364, GSE33630, and GSE58545 cohorts, it was found that the expression of COL4A2 in cancer tissues was significantly greater than normal (p < 0.05)." (PMID 39220121, 2024). "Gene expression of COL1A1, COL1A2, COL6A3, FN1, and THY1 in CAFs as well as COL4A1 and COL4A2 in Angiogenic_EC had a highly significantly positive correlation with the proportion of malignant tumor cells." (PMID 38002057, 2023). "Col1a1, Col1a2, Col2a1, Col3a1, and Col5a2, which were commonly found in normal ECM of mouse, pig, and human breast tissues, were also identified in tumor ECM in addition to Col4a2, Col5a1, Col6a1, Col6a2, Col6a3, and Col7a1." (PMID 36547361, 2022). "The expression of vascular basement membrane markers, Col4a1 and Col4a2, increased dramatically upon tumour infiltration." (PMID 34836954, 2021). "The ectopic expression of miR-29a promotes angiogenesis and tumor cell proliferation through the down-regulation of anti-angiogenic genes such as Col4a2, Spry1 and Timp3." (PMID 28388561, 2017). "In this analysis, we identified subtype‐specific events for Epi‐LumB tumors involving either DNA copy number loss or CpG promoter methylation over DZIP1, TNFSF11, ZIC5, COL4A2, COL4A1 and PCDH8 indicating candidate tumor suppressor genes." (PMID 25468711, 2015).
tumor (continued). "Notably, RARγ peaks were highly enriched near genes involved in cell surface signaling and adhesion, including SERPINE1, ITGB3, ITGA6, and COL4A2, which are known to control both epithelial plasticity and tumor progression." (PMID 41274504, 2025). "Of these hub genes, only four genes, CDK1, NDC80, KIF11, and COL4A2, were shared between the two groups, whereas 189 hub genes from the normal group replaced 101 different hub genes from the tumor group, resulting in protein–protein network differences between the normal and tumor groups." (PMID 40457491, 2025). "Moreover, some studies have shown that miRNAs can regulate tumor angiogenesis by affecting COL4A2 through the PI3K/AKT pathway." (PMID 39220121, 2024). "Both COL4A1 and COL4A2 influence angiogenesis and tumor growth." (PMID 33927218, 2021). "Additionally, miR-21 can enhance tumor metastasis and angiogenesis by inhibiting anti-angiogenic genes such as TIMP3, COl4a2, and Spry1 in tumor-infiltrating myeloid cells." (PMID 34778378, 2021). "Another matrix CAF subcluster, C11, was linked to angiogenesis and highly expressed NOTCH3 (an important receptor in vascularization and angiogenesis), COL18A1 (involved in angiogenesis regulation), COL4A1, and COL4A2, which might promote the proliferation and metastasis of tumor." (PMID 38010945, 2024). "As a member of the ECM, COL4A2 may influence tumor progression through ECM." (PMID 39220121, 2024). "In addition, we confirmed the prevalence of CNV alterations in ARGs in COAD patients, and CNVs seem associated with higher expression of ARGs in tumor tissues, such as NF1, COL4A2, C1GALT1, SPHK1, RUNX1, implying a potential regulatory role of CNVs on the expression of ARGs." (PMID 36505481, 2022). "Genes encoding collagens (COL4A1, COL4A2), collagen-modifying enzyme (PXDN), and other components of the basement membrane (LAMB1, HSPG2) also ranked in the top 10 most enriched Co1 EC markers, indicating that extensive matrix remodeling occurs in GBM during tumor angiogenesis." (PMID 34228647, 2021). "A comparison of these with the 683 KPTN tumor–upregulated genes revealed 130 consistently upregulated genes, including ECM components (COL4A1, COL4A2, COL12A1, VCAN, etc.)and YAP targets (ANKRD1, AXL, CYR61, F3)." (PMID 41480763, 2026). "As the tumor progressed, COL4A1, COL4A2 and COL4A6 expression gradually increased, and COL4A3, COL4A4 and COL4A5 gradually decreased." (PMID 40351420, 2025). "Immunohistochemistry determined the localization of proteins such as COL4A2 in the stroma and ADAM12 in tumour cells." (PMID 40998421, 2025). "The effects of the COL4A2 and AKT pathways on THCA tumor growth in vivo were determined using a mouse model." (PMID 39220121, 2024). "High expression of COL4A2 promotes abnormal activation of the AKT axis, which leads to tumor proliferation." (PMID 39220121, 2024). "Genes such as COL14A1, COL6A1, THBS2, COL4A2 and COL11A1 are involved in tumor migration and invasion." (PMID 37024829, 2023). "The collagen type IV alpha 2 chain (COL4A2) gene simultaneously overexpressed in the cancer and stromal compartment of treated KPC mice tumour tissue." (PMID 38131168, 2023). "Only two genes were found to be differentially expressed between case primary and paired CRLM tumours; albumin (ALB) and collagen type IV alpha 2 chain (COL4A2)." (PMID 34874125, 2022). "FN1, ITGA5, THBS2, and LAMA1 were associated with cell adhesion and metastasis, and the expression of TGFB1, COL4A1, COL4A2, and THBS2 inhibited tumor growth." (PMID 34370778, 2021). "Considering the mutant phenotypes of both COL4A1 and COL4A2 included metabolism phenotype and the GO annotations related to them contained extracellular matrix structural constituent, the two metabolism-related genes may be released by tumor cells and mainly play a role in cancer stroma." (PMID 32704448, 2020).
tumor (continued). "In our NCKU-OrCA-40TN cohort, we noticed that five collagen subunits are upregulated genes in the tumor tissues compared to that in the normal counterparts, including COL1A1 (3.5×), COL4A1 (2.1×), COL4A2 (3.3×), COL4A5 (5.6×), and COL4A6 (9.2×)." (PMID 32244515, 2020). "Upon proteolytic cleavage of COL4A2 and COL4A1, biologically active peptides called Arresten and Canstatin, respectively, are formed that inhibit angiogenesis, proliferation and tumor formation." (PMID 31778112, 2019). "Among the genes involved in the hepatic fibrosis pathway, expression of the IGFBPs, COL4A1, COL4A2, MMP9 and TNFRSF11B was restored in 143BNSC and 143BGBM tumours." (PMID 27551510, 2016). "Four genes (COL4A2, HSPB1, ITGB3, and MAP1A) were significantly less expressed in tumor adjacent stroma in comparison with normal stroma (p values < 0.05)." (PMID 26158290, 2015). "In validation by real-time PCR, four genes (COL4A2, HSPB1, ITGB3, and MAP1A) demonstrated significantly lower expression in tumor-adjacent stroma compared to normal stroma (p value ≤ 0.05)." (PMID 26158290, 2015). "Copy number alterations of MYC (8q24.21), FHIT (3p14.2), WDR60 (7q36.3), COL4A2 (13q34), NFATC1 (18q23), and NCOA3 (20q12) were analyzed in six matched tumor and normal tissue pairs (268–1, 271–1, 272–2, 301–1, 685–1 and 685–2)." (PMID 26360582, 2015). "The results based on t test indicate that COL4A2, HSPB1, ITGB3, and MAP1A were significantly less expressed in tumor adjacent stroma in comparison with normal stroma (p values < 0.05)." (PMID 26158290, 2015). "By using data on DNA copy number changes, we identified genes of potential interest as tumor suppressors in the development of Epi‐LumB and Epi‐Basal tumors, including DZIP1 and COL4A2 (Epi‐LumB) and TENC1 (Epi‐Basal)." (PMID 25468711, 2015). "COL4A2 did not correlate with tumor purity and B-cell infiltration but positively correlated with CD8 + T-cell, dendritic cell, macrophage, neutrophil, and CD4 + T-cell infiltration." (PMID 38907304, 2024). "The analysis suggested that TECs might promote tumor growth and progression through the interaction of COL4A1/COL4A2 with their partner receptors (ITGAV + ITGB8 and ITGA3 + ITGB1) on epithelial cells." (PMID 39093451, 2024). "The predominant predicted tumor-to-microglia interactions in this model were driven by tumor junctional adhesion molecule (JAM) and extracellular matrix (ECM) ligands, such as collagens (e.g., COL4A2, COL6A3) and laminins (e.g., LAMA3, LAMC1)." (PMID 39372744, 2024). "Notably, tumor ECs were featured by upregulation of angiogenesis-related genes including collagens (e.g., COL4A1, COL4A2), PXDN, SPARC and HSPG2, as well as proliferation markers (e.g., MKI67, TOP2A)." (PMID 36138435, 2022). "The mRNA expression level of all six type IV collagen genes (COL4A1, COL4A2 COL4A3, COL4A4, COL4A5 and COL4A6) was higher in metastatic tissue compared to primary tumor tissue, although being significant only for COL4A3 (p = 0.013) and COLA4A4 (p = 0.005) genes." (PMID 35693557, 2022). "Moreover, the mRNA levels of both COL4A1 and COL4A2 were significantly increased in subgroups of HCC patients classified by ethnicity, gender, age, tumor grade, and disease stages compared to normal people." (PMID 31905170, 2020). "However, immunohistochemical analyses revealed that collagen IV is mainly expressed in association with the tumor blood vessels and not from the tumor cells, suggesting that the COL4A2 overexpression detected in GBMs may not be as a result of gene amplification in tumoral cells." (PMID 17002787, 2006). "For example, gene expression levels of COL1A1, COL6A3, and FN1 in CAFs as well as COL4A1 and COL4A2 in Angiogenic_EC were correlated with the proportion of the Cancer_Malig subtype in BC and CRC, indicating these pEMT tumor cells might be regulated by COL1A1 in CAFs and COL4A1 in Angiogenic_EC." (PMID 38002057, 2023).
tumor (continued). "Substantial differences between tumor and neighboring healthy cortex were found in both interstitial matrix proteins, such as collagen 6 (COL6A1, COL6A2, COL6A3), and basement membrane components such as collagen 4 (COL4A1, COL4A2) and laminins (LAMA5, LAMA4, LAMB1, LAMB2, LAMC1)." (PMID 34884982, 2021). "Last but not least, SRF, a tumor-associated transcription factor, may also involve in hepatocarcinogenesis induced by COL4A1 and COL4A2." (PMID 31905170, 2020).
cancer (51 papers, 2012 to 2025). A tumor composed of atypical neoplastic, often pleomorphic cells that invade other tissues. "For instance, increased expression of COL6A1, SDC4, FRAS1, AGRN, and COL4A2 has been observed in different cancer types and reported to be associated with metastasis and poor outcomes in patients." (PMID 37987316, 2023). "Bioinformatics analysis revealed that COL4A2 was closely associated with cancer development." (PMID 39220121, 2024). "MMP9, FN1, FGF13, and COL4A2 are significant genes in the pathways associated with cancer." (PMID 28191466, 2017). "The highest expression of genes encoding Col1a1-2, Col3a1, Col4a1, Col4a2, Col5a1, Col5a2, Col6a1, Col8a1, Col9a3, Col10a1, Col12a1, Col14a1, Col15a1, Col16a1, Col18a1, and Col28a1 were detected in untreated tumors, whose landscapes were dominated by Krt8+ cancer cells." (PMID 39372930, 2024). "Bioinformatics analysis exhibited that COL4A2 plays a significant role in cancer and that the AKT pathway is downstream of COL4A2." (PMID 39220121, 2024). "A previous microarray analysis showed that COL4A2 is a potential biomarker of poor prognosis in Asian cancer patients, but this needs to be further investigated." (PMID 39220121, 2024). "After a series of bioinformatics studies, COL4A2 was found to be highly expressed in human cancer tissues, and we also found a correlation between prognosis, clinical features and COL4A2 expression." (PMID 39220121, 2024). "In comparison to normal tissues, Nos2, Hgf, Lama1, Csf3r, Csf2rb2, Col4a1, Col4a2, Adcy2, Adcy4, Gstm3 and Gstm6 were identified as the most significant genes in cancer pathways." (PMID 37774039, 2023). "Among them, abnormal expression of COL4A1 and COL4A2 disrupts the strict regulation of the ECM and promotes the proliferation and invasion of cancer cells, which is often the main cause of cancer metastasis, recurrence and even death." (PMID 38016970, 2023). "COL4A2 acetylation was increased in cells treated with aspirin, a well‐known anti‐cancer agent.A1AT is the most abundant proteinase inhibitor in extracellular space." (PMID 36453571, 2023). "Expression of COL4A2 is highly correlated with that of COL4A1 in all types of cancers in TIMER2 analysis and exclusively expressed in stromal cells like COL4A1 in single-cell sequencing data (data not shown)." (PMID 35455650, 2022). "Among them, collagen family Col1a1, Col4a2 and Col5a1 are target genes of miR-29a-3p, and promote cancer cells invasion and migration." (PMID 34135859, 2021). "COL4A2 is involved in tight junctions between a variety of human cells and plays a role in the adhesion of cancer cells." (PMID 31886120, 2019). "Among these genes, collagen 3A1 (COL3A1), collagen 4A1 (COL4A1), collagen 4A2 (COL4A2), and laminin 5 were upregulated in the majority of cancer lesions." (PMID 29720137, 2018). "Oktem G found a high level of COL4A2 when cancer stem cells (CSC) were maintained as serum-grown prostate CSC spheroids." (PMID 27906681, 2017). "These genes belong to relevant intracellular signaling pathways in cancer such as PI3K-Akt (COL4A2, MYC, PDGFA, SPP1), proteoglycans (HIF1A, MYC, PLAUR, TGFB1), and Hippo (CTGF, MYC, NF2, TGFB1)." (PMID 29075357, 2017). "Jak-STAT signaling pathway was found to be highly active for differentially expressed genes including Col4A2 in cancer." (PMID 27906681, 2017). "NOTCH3 increases the expression of COL4A2, which makes cancer cells more resistant to anoikis." (PMID 35159353, 2022). "Moreover, the role of COL4A2 in a variety of cancers has also been revealed." (PMID 39220121, 2024). "WIPI2, COL4A2, HDAC4, CUGBP2, PTPRN2 and RUNX2 are Top 6 differential methylation genes, and all of them were reported to take part in regulation of cancers." (PMID 36817452, 2023).